TNF (tumor necrosis factor)
Diseases named in the same sentence as TNF in open-access papers (continued):
Sharing a sentence is not in itself a finding about the gene and the disease.
Stroke (continued). "More specifically IL-1, IL-6, IL-10, IL-17, IL-23, TNFα, transforming growth factor β (TGFβ) and IFNγ are seen to increase after stroke, IL-17, IL-23 and IFNγ being associated with exacerbation of stroke in mice, whereas IL-10 and TGFβ are protective." (PMID 25705177, 2015). "In our study, aLA treatment significantly decreased the expression of major inflammatory cytokines that play an important role during the acute phase of stroke such as TNF-α, MIP1, Iba-1, and IL-1β in RT-PCR." (PMID 25761600, 2015). "Generally, expressions of the cytokines were increased soon after stroke and peaked at 24 h (IL-1β, IL-6, TNF-α) or 48 h (iNOS) post-MCAO." (PMID 25889216, 2015). "High levels of IL-6 and TNF-α predicted incident coronary heart disease, stroke, and congestive heart failure." (PMID 25722960, 2015). "When mice were treated with ibrutinib or PBS on day 0, mature IL-1β protein levels on day 1 after stroke onset were much lower in the brain lysates of ibrutinib-treated mice than in control mice, whereas the IL-6 and TNF-α protein levels were similar." (PMID 26059659, 2015). "Experimental stroke leads to an increase in circulating CD11b+ monocytes which can secrete inflammatory cytokines such as IL- 1β, IL-6, TNFα that maintain the inflammatory response and result in tissue-specific monocyte homing." (PMID 26634148, 2015). "RT-PCR experiments showed a moderate increase in TNF-α expression 24 hr after stroke and a marked increase 3 days after stroke." (PMID 26391329, 2015). "As one of the early initiators of inflammation after stroke, TNFα is an excellent target for neuroprotective treatments." (PMID 24579051, 2014). "Brain cytokine analysis at 24 h indicated that stroke resulted in substantially higher mean levels of IL-4, IL-6, TNF-α, IFN-γ, IL-10, and IL-17A in both C57Bl/6 and FVB mice." (PMID 25477780, 2014). "Interleukin-6 (IL-6) and tumor necrosis factor-alpha (TNF-α) are some of the most studied cytokines in stroke-related inflammation." (PMID 25086655, 2014). "Consistent with previous stroke studies, we also observed an increase in several brain inflammatory cytokines including IL-6, TNF-α, IL-1β in the ischemic hemisphere of vehicle treated animals." (PMID 24618563, 2014). "TNF-α levels at <12 h correlated with infarct volume in all stroke patients and in the large subtype." (PMID 25086655, 2014). "IGF-1 induced Akt activation was preceded by a reduction of blood brain barrier permeability at 4h post-stroke and global suppression of cytokines including IL-6, IL-10 and TNF-α." (PMID 24618563, 2014). "Three studies involving 258 patients measured the levels of TNF-α in serum for 14 days after stroke." (PMID 24707306, 2014). "Consistent with these earlier in vitro studies, we found that knockout of CaMKK β or CaMK IV increased TNFα and IL-6 production in mice after stroke." (PMID 25331941, 2014). "Animal experiments demonstrate that stroke and subarachnoid hemorrhage can up-regulate TNF-α or JNK signaling for BBB permeability." (PMID 25540015, 2014). "Accordingly, both IMAT and Tumor Necrosis Factor-α mRNA levels are increased in paretic limbs of stroke survivors." (PMID 25051047, 2014). "Treatment with rt-PA starting with administration at 20 min after stroke reduced the stroke-induced activation of IL-6, TNF-α, Caspase 3, hsp 32, hsp 70 and MMP-9 significantly in the MCAO." (PMID 24465746, 2014). "One important molecule resulting in cell damage and death following stroke is tumor necrosis factor alpha (TNFα)." (PMID 24579051, 2014). "TNF-α and IL-1β are two well-studied cytokines involved in inflammatory responses after stroke and appeared to aggravate ischemic damage." (PMID 23762140, 2013). "Increased serum and cerebrospinal fluid levels of TNF-α have been found in patients 24 hours, 1 week, and 2 weeks after stroke, and these increases correlate with infarct volume and severity of neurological impairment." (PMID 23431245, 2013).
Stroke (continued). "In contrast, some polymorphisms in TNFα, β-adrenergic receptor 2 (ADRB2) and HLA-DPB1*1701 were protective against stroke." (PMID 23762099, 2013). "Tumor necrosis factor-α (TNF-α) is another major mediator known to be implicated in several neurodegenerative diseases including AD, ALS, PD, and stroke." (PMID 24348193, 2013). "In stroke, microglia already exert neurotoxic effects via release of superoxide, nitric oxide, TNF-α, glutamate and metalloproteinases resulting in direct cytotoxic effects and blood brain barrier damage which are further boosted by tPA." (PMID 23658802, 2013). "Among the large number of cytokines, TNF-α, IL-1 and IL-6, modulate tissue injury in experimental stroke and are therefore potential targets in stroke therapy." (PMID 23514014, 2013). "In this study, treatment of hinokitiol weakens the inflammatory response after embolic stroke in rats, as it is confirmed by the reduction of TNF-α expression in the ischemic brain." (PMID 24285977, 2013). "Upon brain ischemia, microglia/macrophages release inflammatory cytokines such as TNF-α and IL-1β in models of stroke." (PMID 23028794, 2012). "The concentration of IL 6 was in consistent with stroke severity and exogenous administration of TNF-α exacerbated ischemic brain injury." (PMID 23144925, 2012). "Transient MCAo animal models and clinical stroke studies have also demonstrated increased peripheral TNF-α levels." (PMID 22132330, 2011). "Consistently, it was demonstrated that the administration of TNF-α antibodies or TNF-α binding receptors led to a reduction of infarct volumes in experimental animal stroke models." (PMID 22082476, 2011). "Mice that had been preconditioned with LPS prior to ischemia showed a pronounced suppression of the TNF-α pathway following stroke, with reduced TNF-α in the serum." (PMID 21982558, 2011). "A more recent and very limited study in stroke patients reported significant improvement in stroke symptoms following the administration of a TNF-α inhibitor." (PMID 22216404, 2011). "TNFα is considered to play multiple roles in stroke injury mediating many neuroprotective and injurious effects." (PMID 21999375, 2011). "In both telmisartan- and combination pre-treated groups, protein levels of TNF-α in the ipsilateral penumbra were significantly decreased in comparison to the stroke- vehicle group, whereas IL-6 remained unchanged in all pre-treatment groups." (PMID 21901125, 2011). "Inflammatory cytokine and chemokine levels, including IL6, IL1β, MCP-1 and TNFα are elevated in the circulation following stroke." (PMID 21999375, 2011). "Extracellular levels of glutamate and TNF-α have been shown to remain elevated in the infarct region for hours up to days after a stroke, depending on the severity of the cerebral ischemic event." (PMID 21810263, 2011). "In closed head injury, the mRNA and functional activity (cytotoxicity) of TNF-α are increased and increased TNF-α protein levels have been noted by western blot in the brain after stroke." (PMID 21871121, 2011). "The use of MEK1 inhibition might be a way to obtain anti-stroke efficiency since it targets several transcriptional mechanisms activated by cerebral ischemia: (i) receptor upregulation causing enhanced contractility, and (ii) inflammatory gene activation, i.e., for iNOS, IL-1ß, IL-6 and TNF-α." (PMID 20187933, 2010). "The post-stroke progressive sequence of TNF-α expression, selectin upregulation and BBB injury suggests a chronological link between these events." (PMID 20122276, 2010). "These cells are also capable of antagonizing the production of proinflammatory cytokines (TNF-α and IFNγ), that induce secondary brain damage during stroke." (PMID 21192826, 2010). "The most prominent ones after stroke are interleukin-1β (IL-1β), tumor necrosis factor-α (TNF-α) and IL-6." (PMID 21040547, 2010).
Stroke (continued). "Ex vivo, T cells of stroke patients proliferated unimpaired and released increased amounts of the proinflammatory cytokine TNF-α (p<0.01) and IL-6 (p<0.05)." (PMID 20090932, 2010). "For instance, IL10 has been shown to be cerebroprotective in the setting of experimental stroke and soluble receptors of TNF-α limit its cardiotoxicity." (PMID 20300185, 2010). "On mRNA level, BDNF inhibited mRNA expression of brain TNF-α after stroke at both 6 h (0.39 ± 0.01 versus 1.00 ± 0.06, n = 6, P < .05) and 24 h (0.77 ± 0.04 versus 0.91 ± 0.06, n = 6, P < .05) of reperfusion." (PMID 21490702, 2010). "Neurons highly express cytokines such as IL-6, -1β, and TNF-α in neurodegenerative diseases, including AD, spinal cord injury, stroke, and sciatic nerve injury." (PMID 21034511, 2010). "The JNK pathway can be intensely activated by factors such as TNF-α and IL-1β, which are known to be increased after a stroke and have been shown to be involved in the mechanisms underlying ischemia-induced neuron apoptosis." (PMID 23554623, 2010). "There was locally enhanced expression of iNOS, IL-16, IL-1ß and TNF-α in smooth muscle cells in the ischemic region both in the MCA leading to the stroke region and in microvasculature walls." (PMID 20187933, 2010). "This relationship between lesion volume and ambient level of TNFα has been confirmed repeatedly in animal models of focal cerebral ischemia and has even been observed in human stroke victims." (PMID 18947406, 2008). "Montaner and co-workers found positive correlations between elevated blood levels of TNFα or interleukin-6 and the volume of hypoperfused brain observed after bolus-tracking perfusion MRI studies in stroke patients." (PMID 18947406, 2008). "Reactive astrocytes then expressed TNFα immunoreactivity in both the injured hemisphere and in the contralateral hemisphere, beginning within 24 hours of stroke and persisting for up to 18 days afterward." (PMID 18947406, 2008). "The role of TNF-α in stroke remains controversial, and indeed a potentially beneficial role in ischaemic tolerance has been suggested." (PMID 17328808, 2007). "Second, although the TNF-α/IL-6/IL-10 triad is central to stroke inflammation, additional mediators such as interferon-γ, MCP-1, and most notably, the critical driver IL-1β, along with cellular actors like microglia subtypes and peripheral leukocytes, are not explicitly modeled." (PMID 41557608, 2026). "A pharmacovigilance study using the Food and Drug Administration’s Adverse Event Reporting System indicated an increased reporting of CV events such as strokes and ischemic heart disease among patients with RA treated with JAKis compared with anti-TNF therapies." (PMID 41264726, 2026). "Furthermore, while interleukin-1 (IL-1) is a critical mediator in post-stroke inflammation, our model focuses on the TNF-α/IL-6/IL-10 axis to establish a foundational understanding of their core feedback loops." (PMID 41557608, 2026). "Notably, the therapeutic relevance of TNF-α critically depends on the timing of intervention relative to stroke onset." (PMID 41683844, 2026). "In stroke survivors, there were observed higher levels of plasma TNF-α compared to controls as well as increased TNF-α mRNA expression in paretic muscles, pointing towards heightened inflammatory activity in these muscles that leads to muscle wasting and metabolic dysfunction." (PMID 41598337, 2026). "A central finding of this work is the model’s ability to reproduce the temporal decoupling between pro- and anti-inflammatory cytokines, with TNF-α and IL-6 rising sharply during the early post-stroke phase, and IL-10 emerging only after a defined temporal threshold." (PMID 41557608, 2026). "Simulations of the post-stroke cytokine network over a 72-hour period yielded temporally distinct trajectories for tumor necrosis factor-alpha (TNF-α), interleukin-6 (IL-6), and interleukin-10 (IL-10), reflecting the transition from pro-inflammatory activation to immune resolution." (PMID 41557608, 2026).
Stroke (continued). "The proportion of monocytes capable of producing TNF-α after stroke is lower than control subjects." (PMID 41455014, 2025). "Additionally, a decrease in TNF-α concentration within 72 to 144 h after stroke was correlated with clinical improvement." (PMID 40362186, 2025). "It has been reported that within 1 year after stroke onset, inflammatory markers such as interleukin-6 (IL-6), interleukin-10 (IL-10), and tumor necrosis factor-alpha (TNF-α) are significantly elevated, with notable increases in the IL-6/IL-10 and TNF-α/IL-10 ratios." (PMID 41458124, 2025). "Similarly, in the brain, activated microglia and astrocytes in stroke or neurodegeneration release IL-1β, TNF-α, IL-6, and matrix metalloproteinases that disrupt the blood–brain barrier and kill neurons and damage neural connections." (PMID 41462689, 2025). "Anti-cytokine therapies (e.g., IL-6 or TNF-α inhibitors) may also hold promise in modulating the systemic inflammatory response post-stroke." (PMID 40724982, 2025). "A decrease in inflammatory mediators, including the expression of NF-κB target genes such as ICAM-1, inducible nitric oxide synthase (iNOS), cyclooxygenase-2 (COX-2), tumor necrosis factor-α (TNF-α), and interleukin-1β (IL-1β), was also observed in the mouse model of experimental stroke." (PMID 41302473, 2025). "Emerging treatments targeting IL-6 and TNF-alpha present promising advances in post-stroke care." (PMID 39859987, 2025). "Other positive effects of anthocyanin preconditioning in inducing stroke have also been mentioned, such as improving spontaneous activity and memory, and reducing the levels of molecules involved in the inflammatory response such as TNF-a, IL-1B, and IL-6." (PMID 40724240, 2025). "Recent studies have also highlighted the dynamic interplay between IL-6 and TNF-alpha, suggesting that the balance between these cytokines may significantly affect the inflammatory environment in the post-stroke brain." (PMID 39859987, 2025). "Similarly, pro-inflammatory cytokines IL-1β, IL-6 and TNF-α were significantly upregulated in the Stroke group relative to Sham controls (p < 0.001)." (PMID 41388741, 2025). "Similarly, TNFα levels increase in the brain and blood following stroke and increase neuroinflammation." (PMID 40362325, 2025). "Furthermore, we found a significant increase in TNF-α and IL- 6 in pMCAO stroke mice, which was significantly suppressed in KG diet pre-treated mice following PT stoke consistent with the previous studies." (PMID 40272769, 2025). "This cascade effect explains why inflammatory factors (e.g., TNF-α, IL-1β) are commonly elevated in both Osteoporosis and stroke patients, and also provides a molecular basis for the “inflammation as a common pathological basis” hypothesis of comorbidity." (PMID 41379792, 2025). "After stroke, microglia undergo significant morphological changes, from small branching structures to large amoeba-like structures, that produce pro-inflammatory factors, including IL-1β, IL-6 and TNF-α." (PMID 40004043, 2025). "Furthermore, the exacerbating role of inflammatory cytokines such as IL-6 and TNF-α in stroke outcomes is well-established." (PMID 40313968, 2025). "Additionally, TMAO levels are positively correlated with the expression of various pro-inflammatory cytokines, such as IL-6 and TNF-α, which play a crucial role in post-stroke neuroinflammation." (PMID 40625834, 2025). "Following a stroke, immune cells, including dendritic cells and macrophages, detect pathogens and damage signals within the gut, thereby activating local immune responses through the secretion of pro-inflammatory cytokines, such as IL-6, IL-1β, and TNF-α." (PMID 40625834, 2025). "Moreover, stroke survivors with cognitive impairment exhibit increased inflammation, with C-reactive protein, IL-6, and TNF-α serving as predictors of PSCI." (PMID 39911922, 2025).
Stroke (continued). "Inflammation plays a pivotal role in the pathogenesis of stroke, with key mediators —specifically IL-1β (neutrophil recruitment), IL-6 (acute-phase amplification), and TNF-α (neuronal apoptosis)— confirmed to drive secondary injury and correlate with ICH severity/prognosis." (PMID 40765613, 2025). "Thus, PPARα likely curtails neuroinflammation following stroke through the regulation of TNFα signaling-related genes." (PMID 40362325, 2025). "Beyond its serotonergic modulation, preclinical evidence indicates that vortioxetine suppresses pro-inflammatory cytokines (e.g., IL-6, TNF-α) through 5-HT3 receptor antagonism and enhances synaptic plasticity via 5-HT1A receptor agonism, both mechanisms implicated in post-stroke recovery." (PMID 40144659, 2025). "The post-stroke inflammatory response further reinforces this effect, as activated microglia, astrocytes, and infiltrating immune cells release cytokines—such as TNF-α, interleukin-1β (IL-1β), and S100 proteins—which are also implicated in pre-metastatic niche formation." (PMID 40909970, 2025). "Elevated TNF-α levels have also been shown to increase blood-brain barrier permeability, exacerbating neuroinflammation and tissue damage during the acute phase of a stroke." (PMID 41050669, 2025). "TNF-α inhibitor use was associated with increased risks of MI (aHR, 1.86; 95% CI, 1.03–3.35), TB (aHR, 2.68; 95% CI, 1.47–4.90), and CKD (aHR, 2.27; 95% CI, 1.51–3.42), alongside a reduced risk of stroke (aHR, 0.51; 95% CI, 0.27–1.00)." (PMID 41007780, 2025). "Studies have revealed that the NF‐κB signaling pathway is over‐activated in microglial cells following a stroke, serving as a crucial regulator of the inflammatory response by driving the transcription of downstream pro‐inflammatory cytokines such as IL‐1β, TNF‐α, and IL‐6." (PMID 40237440, 2025). "By delving into the molecular underpinnings of IL-6 and TNF-alpha involvement in ischemic stroke, we hope to uncover novel insights that could pave the way for more effective and targeted interventions in stroke management." (PMID 39859987, 2025). "Similarly, the relationship between inflammation, specifically through cytokines such as IL-6 and TNF-alpha, and stroke severity has been extensively studied." (PMID 39859987, 2025). "On the other hand, the persistence of high TNF-a levels after the second atherothrombotic stroke showed a ROC curve of 0.88 (95% CI: 0.85.0.91) with an optimal cut-off of >24 pg/mL, which was independently associated with atherothrombotic stroke recurrence (adjusted OR 21.26; 95% CI: 12.42–37.59)." (PMID 40094903, 2025). "Although TNF-α, a key regulator of neuroinflammation, rises 1–3 h after stroke onset, it may confound stroke severity with other inflammatory conditions." (PMID 40362186, 2025). "Furthermore, a longitudinal study indicated that elevated levels of TNF-α and interleukin-1 beta (IL-1β) within 2 weeks post-stroke are strongly correlated with the occurrence of PSD." (PMID 41458124, 2025). "When examining the molecular mechanism involved, some studies further demonstrated that long sleep duration was associated with increased levels of inflammatory cytokines, including IL-6 and tumor necrosis factor-alpha (TNF-α), which contribute to the pathogenesis of stroke." (PMID 39981486, 2025). "Systemic immunosuppression after stroke is characterised by an imbalance between proinflammatory/cellular and anti-inflammatory/humoral predominant mechanisms, with a reduction of pro-inflammatory factors including TNF." (PMID 41455014, 2025). "The identification of IL-6 and TNF-alpha as key contributors to post-stroke outcomes suggests that therapeutic strategies targeting cytokine modulation could be pivotal in improving rehabilitation trajectories and reducing long-term disability." (PMID 39859987, 2025).